INS (insulin)
Diseases named in the same sentence as INS in open-access papers (continued):
Sharing a sentence is not in itself a finding about the gene and the disease.
metabolic disorders (continued). "Of the resulting 44 SM gene modules, 14 were significantly associated with pathways related to metabolism or metabolic disease, such as oxidative phosphorylation, insulin signaling, and stress response." (PMID 32350364, 2020). "Obesity is often accompanied by metabolic disorders including insulin dysregulation, which itself has been associated with altered microbiome composition and reduced bacterial richness in humans." (PMID 32131835, 2020). "Psychological issues are associated with metabolic diseases via the accumulation of visceral fat through hormonal dysregulation, including that of insulin." (PMID 32471118, 2020). "Up to now, a number of factors have been proposed to cause metabolic disorder in DM patients, including β-cell dysfunction, insulin resistance, and bodyweight gain, or a combination of these." (PMID 31821362, 2019). "The reduction and insufficiency of insulin caused metabolic disorders of glucose and also lipids and protein." (PMID 30937310, 2019). "Metabolic disruptions like above for OGTT, lipid and insulin profiles can increase the long-term risk of various metabolic diseases such as T2DM, IR and CVD." (PMID 31308416, 2019). "Insulin secretion and insulin action are essential for blood glucose homeostasis, and defects in either process cause metabolic diseases, such as T2DM." (PMID 31867052, 2019). "Maternal high-fat (HF) feeding emerged as a risk factor for metabolic disorders involving abnormal glucose homeostasis and reduced whole-body insulin sensitivity in offspring." (PMID 31717308, 2019). "IR causes metabolic disorders by inducing an increase in blood glucose and insulin levels due to decreased susceptibility to insulin in muscle, liver, and adipocytes." (PMID 31212845, 2019). "Especially type 2 diabetes (T2D) is a highly complex, multifactorial metabolic disease, characterized by a progressive pancreatic β-cell failure (relative insulin deficiency), decreased insulin action and peripheral insulin resistance." (PMID 31396030, 2019). "In particular, the link between metabolic disorders and cystic ovarian disease has been studied in animal models, specifically for the insulin resistance as a pathogenic factor." (PMID 31307376, 2019). "And the activation of PKCε serves as one underlying mechanism linking hepatic insulin resistance, hepatosteatosis, and impaired glucose metabolism in metabolic disease models." (PMID 30036185, 2018). "Skeletal muscle plays an important role in glucose disposition and defects in skeletal muscle function and insulin responsiveness are associated with an increased risk of metabolic disease." (PMID 29651255, 2018). "Liberated FFAs induce inflammatory responses and alter insulin sensitivity, potentially resulting in metabolic disorders and increased risk of sepsis." (PMID 30315247, 2018). "The new onset of metabolic disorders is often caused by the use of immunosuppressant medications such as cyclosporine, tacrolimus, and glucocorticoid which attack the insulin signaling pathway by changing adipose enzymes." (PMID 28194427, 2017). "Short-term fish oil supplementation is associated with increasing the insulin sensitivity among those people with metabolic disorders." (PMID 28673352, 2017). "It is a metabolic disorder characterized by the lost of blood glucose level’s control which increased as a result of the deficiency of insulin secretion or insulin effect." (PMID 28472941, 2017). "Taken together, diosmin improves metabolic disorders mainly through an activation of I-2R in diabetic rats, particularly in the insulin-deficient state." (PMID 28665324, 2017). "High insulin indicative of IR or insulin dysregulation (ID) in EMS horses is one of the features associated with this metabolic disorder." (PMID 27613127, 2016). "Insulin promotes the storage of excess glucose and its conversion to fat, leading to increased adiposity, a major risk factor for the development of metabolic disease." (PMID 27478532, 2016).
metabolic disorders (continued). "In recent years, the usefulness of Orz has been studied for the treatment of metabolic diseases, as it acts to ameliorate insulin activity, cholesterol metabolism, and associated chronic inflammation." (PMID 27517904, 2016). "The remaining pathways included the ATP-based transporters, basic cellular control and homeostasis pathways, PPAR, insulin signaling, and adipocytokine signaling, many of which have already been associated with metabolic disorders." (PMID 27656641, 2016). "In contrast, acute exercise also increases oxidative stress and SAPK signaling, yet is reported to enhance insulin sensitivity and reduce the risk of metabolic disease." (PMID 27695421, 2016). "Regulation of glycemic fluctuations and postprandial glycaemia are important for the long-term maintenance of insulin sensitivity and lowered risk of metabolic disease." (PMID 28119617, 2016). "DM2 (a metabolic disease resulting from defects in insulin production, insulin activity, or both) can cause micro- and macrovascular complications." (PMID 26137892, 2015). "Aberrantly high Trib3 levels are detected in insulin-resistant humans and a population variant Trib3Q/R84 associated with predisposition to metabolic disease dominantly blocks insulin signaling in cell culture." (PMID 25329475, 2014). "Hypothalalmic inflammation disrupts energy homeostasis by leading to pathogenic changes in insulin signaling, feeding and body weight and thus is a major target for the prevention and treatment of various metabolic diseases including DIO and T2DM." (PMID 24674717, 2014). "Anthropometric outcomes were measured and fasting blood glucose, insulin and lipid profile were analysed to determine metabolic disease risk and prevalence." (PMID 25200747, 2014). "Collectively, our results indicated that Tff3 peptides are involved in glucose homeostasis and insulin sensitivity, providing a promising peptide on new therapies against the metabolic disorders associated with T2DM." (PMID 24086476, 2013). "Type II diabetes accounts for about 90% of the disease, and is characterized by peripheral insulin resistance and impaired insulin secretion, which is often associated with lipid and lipoprotein disorders." (PMID 22016649, 2011). "Metabolic disorders are associated with mitochondrial loss and dysfunction and pharmacological strategies to induce mitochondrial proliferation improve insulin signaling and energy metabolism." (PMID 19500359, 2009). "Lipocalins are emerging as central regulators of peripheral insulin sensitivity and have been implicated in metabolic diseases." (PMID 19390610, 2009). "T2D is a complex metabolic disorder which is caused by both decreased insulin sensitivity, and impaired insulin secretion due to pancreatic β-cell defects." (PMID 19368707, 2009). "Weight loss appears to improve several metabolic parameters, including lipid metabolism, amino acid profiles, and inflammatory markers, which may contribute to better insulin sensitivity and reduced risk for metabolic diseases." (PMID 40507103, 2025). "Beyond that, very little is known about the role of cytokines in INS signalling in the intestine; nevertheless, metabolic diseases are known to be associated with significant changes to the immune component in the intestine, which results in an aberrant inflammatory environment." (PMID 40940769, 2025). "Previous studies have shown that adults with low grip strength exhibit various mechanisms linked to the pathophysiology of metabolic diseases, such as insulin resistance, chronic inflammation, intramuscular fat accumulation, mitochondrial dysfunction, and decreased myokine secretion." (PMID 40870518, 2025). "Low adiponectin levels are linked to metabolic disorders; increasing adiponectin could enhance insulin sensitivity and reduce inflammation." (PMID 40013194, 2025). "In addition, the community is at risk of developing metabolic disorders (61%) as determined by the insulin secretion coefficient." (PMID 40426847, 2025).
metabolic disorders (continued). "Indirect effects occur by reducing appetite and delaying gastric emptying, GLP-1 may help to reduce body weight and insulin sensitivity, which in this case alleviates metabolic disorders commonly associated with MASLD." (PMID 40244398, 2025). "However, the effect of maternal Sst deficiency on glucose and insulin metabolism in offspring and metabolic disease risk in their adult life has been poorly understood." (PMID 40066865, 2025). "DM is a metabolic disease caused by insufficient insulin, and insulin action malfunctions." (PMID 39847549, 2025). "Taken together, these data suggest that GNAS mutations or variants that reduce Gαs activity could contribute to metabolic disorders, including suboptimal insulin secretion." (PMID 40526441, 2025). "Furthermore, green tea extract and EGCG reduced metabolic disorders caused by bisphenol A by acting as antioxidants and anti-inflammatory agents, regulating lipid metabolism, and improving insulin signaling." (PMID 40969408, 2025). "It remains unclear whether targeting P-Rex2 would be beneficial in tackling metabolic disease, as P-Rex2 deficiency increased glucose clearance but reduced insulin sensitivity." (PMID 40764335, 2025). "Interestingly, these miRNAs are also involved in the insulin signaling pathway and glucose metabolism, supporting their potential as a functional proxy of zinc status in association with metabolic disorders." (PMID 41228448, 2025). "Some serious metabolic diseases are related to loss of insulin sensitivity by cells." (PMID 38357499, 2024). "Therefore, the balance of SCD activity is crucial to health, and its deficiency induces metabolic disease, including adiposity decrease, lipid oxidation, and insulin sensitivity increase." (PMID 39327557, 2024). "Notably, keystone taxa that became more prominent over time were associated with anti-adipogenesis, improved insulin sensitivity, and reduced metabolic disease risk." (PMID 38806467, 2024). "Furthermore, because the IRS/PI3K signaling pathway ensures that hepatocytes respond effectively to insulin to maintain glucose homeostasis, its disruption is closely associated with IR-induced metabolic disorders." (PMID 39337550, 2024). "This aligns with broader nutritional science, emphasizing the importance of minimizing UPF consumption to mitigate not only GDM risk but potentially other metabolic disorders as well, given the multitude of adverse mechanisms through which UPFs affect glucose metabolism and insulin sensitivity." (PMID 38750456, 2024). "Furthermore, CR enhances insulin sensitivity and improves glucose tolerance, factors crucial for maintaining metabolic health and reducing the risk of metabolic disorders." (PMID 38728252, 2024). "T2DM is one of the most common metabolic disorders worldwide and its development is primarily caused by a combination of two main factors: defective insulin secretion by pancreatic β‐cells and the inability of insulin‐sensitive tissues to respond to insulin." (PMID 39410716, 2024). "For example, ambient temperature may alter how insulin and its counterregulatory hormones maintain glucose homeostasis, create a risk for metabolic disease, or affect insulin dosing for individuals treated with insulin." (PMID 38354854, 2024). "This study provides insights into the characteristics of impaired glucose-insulin metabolism and the underlying factors that could be targeted for early intervention and prevention of metabolic diseases in LBW animals." (PMID 38596462, 2024). "Metabolic disorders are often linked to alterations in insulin signaling." (PMID 37002295, 2023).
metabolic disorders (continued). "It is well known that insulin resistance (IR) caused by insufficient insulin secretion during pregnancy, may lead to metabolic disorders, mainly GDM and related pathologies." (PMID 36829900, 2023). "The pathogenesis of MAFLD is mainly related to metabolic disorders and altered glucose-insulin homeostasis; therefore, vitamin K may reduce the risk of MAFLD by stabilizing glucose-lipid metabolism." (PMID 37305083, 2023). "Among these immune populations, CD11c+ cells are considered a therapeutic target for obesity-associated metabolic disorders because ablation of this population could alleviate the obese-induced insulin sensitivity." (PMID 36781473, 2023). "Understanding the intricate relationship between insulin secretion, receptor responsiveness, and the consequences of continuous insulin exposure is critical in elucidating the mechanisms underlying IR and related metabolic disorders." (PMID 37446104, 2023). "A role for PKCδ in regulating insulin sensitivity and glucose tolerance suggests that loss of PKCδ function may improve the outcome of metabolic diseases." (PMID 37611829, 2023). "The increased circulating IL-6 levels from contracting skeletal muscle may enhance insulin sensitivity, lipolysis, and fat oxidation, therefore reducing the risk of metabolic disorders." (PMID 36834025, 2023). "Moreover, Aspergillus has been linked to adiposity and related metabolic disorders including insulin resistance, arterial blood pressure, and inflammation." (PMID 35654937, 2022). "Brown and beige adipocytes act as a metabolic sink for glucose and lipids, so the age-related impairment in their function may contribute to an insulin-resistant state and metabolic disease risk." (PMID 35979379, 2022). "It has been indicated that immune cells such as macrophages and neutrophils would reside in or infiltrate liver parenchyma under obese conditions and cause chronic inflammation or metabolic disorders that decrease insulin sensitivity thus leading to the development of IR." (PMID 35692404, 2022). "The importance of insulin clearance as a risk factor for metabolic disease is becoming recognized and may be treatable." (PMID 35163746, 2022). "This form of glucose is insulin resistant and predisposes the infants to metabolic disease." (PMID 36613847, 2022). "Since chronic high levels of blood FGF21 are a risk factor for several metabolic diseases, it is necessary to evaluate whether insulin dose simply affects FGF21 secretion and/or FGF21-related metabolic diseases." (PMID 35192641, 2022). "For instance, IUGR animals (caused by uterine artery ligation) had changes in organ growth and development of islet β cells and insulin-sensitive tissues, and increased susceptibility to metabolic diseases such as DM later in life, which can be triggered by epigenetic mechanisms." (PMID 36438765, 2022). "When TAAR1 is activated in these organs, it may regulate digestion and food absorption, and insulin is secreted to counteract the metabolic disorders caused by olanzapine." (PMID 35458749, 2022). "In an animal study, the metabolic disorders associated with chronic exposure of adult rats to lead toxicity, including insulin insensitivity and weight gain, may be resulting from altered methylation of metabolism-related genes." (PMID 35187171, 2022). "These, in turn, may reduce the ability of adipose tissue to buffer excess nutrients and lead to a pro-inflammatory and insulin-resistant state, ultimately increasing the risk of obesity and metabolic diseases." (PMID 35979379, 2022). "It seems that the silk cocoon 's antioxidant properties can reduce the serum glucose level by compensating for the pancreatic function deficits by partially correcting the metabolic disorders caused by increased blood glucose and by increasing insulin secretion." (PMID 36311276, 2022).
metabolic disorders (continued). "The molecular mechanism linking lipid-based abnormalities to metabolic disorders has been shown to be associated with insulin-mediated FOXA2 repression in obese and high-fat diet states, leading to elevated triglycerides and reduced plasma high-density lipoprotein (HDL) levels." (PMID 35973994, 2022). "Furthermore, functional enrichment analysis showed that the poor prognosis of high-risk population was related to the metabolic disorders caused by inadequate insulin secretion, which was fueled by neuroendocrine abnormality." (PMID 34090418, 2021). "In different studies, it has been observed that a healthy dietary pattern, such as frequent consumption of fiber, including monounsaturated and polyunsaturated fats, can improve insulin sensitivity, increase antioxidant defense, and thus reduce the risk of metabolic disorders." (PMID 34960024, 2021). "GSEA enrichment analysis revealed that many signaling pathways were significantly enriched in the high-risk subgroup, including pathways related to metabolism and metabolic diseases, such as pyruvate metabolism, glycolysis gluconeogenesis, and insulin signaling pathways." (PMID 35223866, 2021). "Thereby, we hypothesize that Mof haploinsufficiency may affect insulin sensing or signaling, leading to aberrant global glucose homeostasis and thereby predisposing Mof+/− animals to the development of metabolic disorders." (PMID 34707105, 2021). "Finally, although the implication of group X (sPLA2‐X) in metabolic diseases is still uncertain, sPLA2‐X activity was associated with suppression of insulin secretion in mice." (PMID 33433056, 2021). "Type 2 diabetes (T2D) is a multifactorial metabolic disease characterised by impaired glucose haemostasis that is primarily caused by lack of response of peripheral tissues to insulin and/or insufficient production/secretion of insulin by β cells of pancreas." (PMID 34258292, 2021). "However, reducing body weight and body fat through regular exercise decreases TNF-α concentration and enhances inflammation and insulin sensitivity, thereby lowering the risk of cardiovascular disease and metabolic disorders." (PMID 34200794, 2021). "Mechanically, functional enrichment analysis showed that the risk signature prediction might be relevant to the metabolic disorders caused by insufficient insulin secretion, which was fueled by neuroendocrine abnormality." (PMID 34090418, 2021). "Future studies of the role of aberrations of the glucose-insulin homeostasis in the common aetiology and mechanisms of metabolic disorders, present during pregnancy, and their association, both as single conditions and–particularly–in combination, with CHDs are needed." (PMID 34043700, 2021). "Mechanically, muscle mass loss of extremity circumference could influence insulin sensitivity, fat oxidation, and glucose metabolism and promote metabolic disorders." (PMID 34876164, 2021). "Therefore, in this review we will discuss the particular effect of the mentioned metabolic disorders on brain plasticity and the potentiality for inflammatory and associated insulin-resistance mediators as therapeutic targets in AD." (PMID 33967682, 2021). "Metabolic diseases such as diabetes mellitus and cardiovascular disease manifest through a combination of various risk factors, such as low-grade inflammation, metabolic disorders, excess lipid accumulation, and loss of insulin sensitivity." (PMID 32340247, 2020). "Similarly to Prdx6, SIRT1 has shown to modulate insulin release and to be implicated in metabolic disorders." (PMID 32316601, 2020). "When fed the same calorie-rich diet as controls, male offspring of cholestatic fathers showed features associated with the initial stages of metabolic disease, including higher fasting insulin levels and enlarged livers with increased hepatic triglyceride content." (PMID 29795465, 2019).